WDR70 (WD repeat domain 70)
Synonyms: FLJ10233
Tractability: Small molecule: a structure with a bound ligand is known. PROTAC: UniProt records ubiquitination sites on it; ubiquitination databases record sites on it; its protein half-life has been measured.
Gene: Protein-coding gene on chromosome 5 (37,379,281 to 37,753,435, forward strand). Ensembl gene ENSG00000082068.
Subcellular location (Human Protein Atlas): Cytosol; Mitochondria
Pathways (Reactome):
Metabolism of RNA: mRNA Splicing - Major Pathway
Gene Ontology:
Molecular function: enzyme binding
Biological process: mRNA splicing, via spliceosome
Cellular component: spliceosomal complex; U2-type catalytic step 1 spliceosome; nucleoplasm; site of double-strand break
Genetic constraint (gnomAD): Loss-of-function variants: 44 observed, 77.45 expected, observed/expected ratio (o/e) 0.57, 90% interval 0.44 to 0.73. The upper end of that interval is the gene's LOEUF score, 0.73, which puts it in group 2 of 6, group 1 being the genes least tolerant of losing a copy. Missense variants: 555 observed, 780.8 expected, observed/expected ratio (o/e) 0.71, 90% interval 0.66 to 0.76. Synonymous variants: 259 observed, 260.38 expected, observed/expected ratio (o/e) 0.99, 90% interval 0.9 to 1.1.
Homologues: Orthologues: chimpanzee WDR70 (99% identical), macaque WDR70 (98% identical), rabbit WDR70 (95% identical), dog WDR70 (95% identical), guinea pig WDR70 (94% identical), pig WDR70 (94% identical), rat Wdr70 (93% identical), mouse Wdr70 (91% identical), tropical clawed frog wdr70 (73% identical), zebrafish WDR70 (53% identical), Drosophila melanogaster CG5543 (41% identical), Caenorhabditis elegans gad-1 (32% identical).
Diseases named in the same sentence as WDR70 in open-access papers:
WDR70 is named in the same sentence as 3 diseases in open-access papers, as found by Europe PMC text mining. Sharing a sentence is not in itself a finding about the gene and the disease. The quoted sentences say what the papers report.
prostate carcinoma (1 paper, 2023). A carcinoma that arises from epithelial cells of the prostate gland.
cancer (1 paper, 2023). A tumor composed of atypical neoplastic, often pleomorphic cells that invade other tissues. "For example, WD Repeat Domain 70 (WDR70) and NEDD8 ubiquitin-like modifier (NEDD8) are both essential genes in multiple cancer lines." (PMID 37845222, 2023).
tumor (1 paper, 2013). "The function of FBN3, PCNXL3, SFXN3, SRGAP1, VN1R5 and WDR70 have been only marginally evaluated, and their role in the molecular signaling of tumor cells remains largely understudied." (PMID 23577124, 2013).